TNF (tumor necrosis factor)
Diseases named in the same sentence as TNF in open-access papers (continued):
Sharing a sentence is not in itself a finding about the gene and the disease.
Cognitive impairment (continued). "Furthermore, elevated TNF-α levels correlated with higher Aβ1-42 levels, supporting the hypothesis that inflammation can exacerbate amyloid pathology, leading to cognitive deficits." (PMID 37759689, 2023). "In addition, high TNF-α (P<0.001, adjusted P <0.001), IL-1β (P=0.033, adjusted P=0.132), and IL-6 (P=0.012, adjusted P=0.048), but not IL-17 (P=0.554, P=1.000 after adjustment) were correlated with cognition impairment occurrence." (PMID 35239774, 2022). "We previously addressed IL-6 and TNF-’s many neurotoxic actions, which, when coupled with other neurotoxic substances like LPS and lipid peroxidation, may produce neurotoxicity and, hence, explain the cognitive deficits and phenome of schizophrenia." (PMID 36256663, 2022). "Furthermore, we found that the cognitive disorder and altered intestinal microflora structure in preterm rats were associated with decreased levels of 5-HT, GABA, and BDNF, and increased levels of GR, CRH, IL-6, and TNF-α in serum." (PMID 36061856, 2022). "In addition, TNF-α and NIHSS score ≥5 were related to a high risk of cognition impairment." (PMID 35239774, 2022). "Plasma level of tumor necrosis factor-α (TNF-α) has a crucial role in triggering neuroinflammation through glial activation, is maintained at a low level in cognitively normal individuals, while it increases in patients with AD and mild cognitive impairment (MCI)." (PMID 35434157, 2021). "Interestingly, although much work has been carried out in mice, prior research in humans has suggested that TNF-α-driven processes may contribute to cognitive impairments, which could also negatively influence academic results." (PMID 33156854, 2020). "In support of the role of TNFα as a central mediator of Aβ action, excess cytokine, at a level 25 times higher than controls, has been reported in the cerebrospinal fluid of patients with AD, which correlates with progression from mild cognitive impairment to AD." (PMID 26345473, 2015). "Therefore, considering the existing evidence supporting a role for cytokines, particularly TNF-α, on LPS-induced cognitive impairment, we thought that the memory-improving effects of spermine could involve a decrease of cytokine levels in the hippocampus." (PMID 25573647, 2015). "A single systemic treatment with the TNF-α synthesis inhibitor 3,6′-dithiothalidomide 1 h post injury prevented the mTBI-induced TNF-α elevation and fully ameliorated the neuronal loss (NeuN), elevations in astrocyte number (GFAP) and BID, and cognitive impairments." (PMID 25879458, 2015). "In accord with this, Janelsins and colleagues noted an elevated expression of TNF-α transcripts within the entorhinal cortex of 3xTg-AD mice at 2 months, prior to the appearance of amyloid and tau pathology, and this increase correlated with the onset of cognitive deficits in these mice." (PMID 22642825, 2012). "Therefore, pharmacological strategies aimed at decreasing TNF-α synthesis may be useful to restore neuronal functions and consequently reduce cognitive deficits during chronic neuroinflammation." (PMID 22277195, 2012). "Increased pro-inflammatory cytokines levels (TNFα, Interleukin-6, Interleukin-1β), combined with decreased levels of anti-inflammatory cytokines (Interleukin-10), have been correlated with cognitive deficits suggesting that early inflammatory changes may be detrimental." (PMID 22838967, 2012). "The areas under the ROC curve (AUC) for IL-6, TNF-α, and NSE in assessing cognitive impairment were 0.842, 0.833, and 0.855, respectively." (PMID 41624546, 2026). "Multiple studies have reported elevated TNF⍺, IL6, IL1β, and hyperactive microglia in AD patients with early mild cognitive impairment (MCI), contributing to LTP impairment via Aβ-induced proinflammatory cytokines." (PMID 40498003, 2025).
Cognitive impairment (continued). "Elevated C-reactive protein (CRP), interleukin-6 (IL-6), and tumor necrosis factor-α (TNF-α) identify clinically relevant subgroups of patients characterized by greater severity, cognitive impairment, and poor treatment response." (PMID 41090786, 2025). "Dysregulated cytokine release, including elevated levels of tumor necrosis factor-alpha (TNF-α), interleukin-1β (IL-1β), and interleukin-6 (IL-6), exacerbates neuronal injury and cognitive impairment." (PMID 40822471, 2025). "On the other hand, the levels of tumor necrosis factor (TNF)-α and interleukin 6 (IL-6) were significantly higher in MHD patients with cognitive impairment." (PMID 40950978, 2025). "Intraperitoneal injection of hemin induced cognitive impairment, increase of CD91 + cells, up-regulation of TNF-α and IL-1β, down-regulation of IL-6, activation of microglia, and activation of the TLR4/MyD88/NF-κB signaling pathway in rat brain." (PMID 38183122, 2024). "Drugs that affect these processes include TNFα blocking antibodies and MAPK p38 inhibitors that reduce cognitive impairment when given for other inflammatory conditions." (PMID 39717349, 2024). "Among the key targets, increased levels of the inflammatory cytokines interleukin-6 (IL6), tumor necrosis factor (TNF), and interleukin-1β (IL1B) all independently contribute to cognitive impairment." (PMID 37233418, 2023). "In Alzheimer’s disease, increased levels of tumor necrosis factor (TNF)-α and lower levels TNF-β were detected in the cerebrospinal fluid (CSF) of mild cognitive impairment patients when compared with the controls." (PMID 37259454, 2023). "Psychological distress was involved in chemotherapy‐related cognitive impairment (CRCI) by increasing IL‐1β, TNF‐α, and IL‐4 levels." (PMID 36965094, 2023). "Increased levels of cytokines, including tumor necrosis factor (TNF), accelerate cognitive decline and transition from mild cognitive impairment to AD." (PMID 37006470, 2023). "In the current study, compared with the Control group, the hippocampal levels of IL-1β, IL-6, and TNF-α were increased in the MLPS group, which likely contributed to the cognitive impairment induced by maternal LPS exposure." (PMID 38074521, 2023). "By establishing an animal model of IL-17A overexpression, we discovered that IL-17A increases the level of TNF-α in the brain through the TLR4/NF-κB signalling pathway, aggravates neuroinflammation, and thus exacerbates cognitive impairment." (PMID 38098004, 2023). "For example, pro-inflammatory factors such as leptin, IL-6, TNF-α which are secreted by adipocytes can cross the BBB and lead to neuroinflammation, which plays a role in cognitive impairment and AD." (PMID 37457589, 2023). "In contrast, an identical VX-765 treatment regimen and Casp1 KO in 5- to 8-month-old J20 normalized Iba1+-microglia, elevated hippocampal TNF-α and CXCL1, and reversed or prevented the onset of cognitive impairment." (PMID 36220815, 2022). "In doxorubicin (DOX)-impaired rats, galangin significantly mitigates cognitive impairment and neurotoxicity via the NOX-1/Nrf-2/HMGB1/TLR4 and TNF-α/MAPKs/RIPK/MLKL/BDNF pathways." (PMID 36015161, 2022). "For instance, in an animal study using male Wistar rats, chronic sleep deprivation induced elevated inflammatory levels of Tumor Necrosis Factor alpha (TNF- α) and interleukin (IL)-1β, which led to anxiety-like behavior and cognitive deficits." (PMID 36212194, 2022). "HMGB1/TLR4/IL-1β/IL-1R pathway, HMGB1/TNF-α/TRADD pathway, and TRAF-2 are the key initiators of neuroinflammation for epilepsy and cognitive impairments." (PMID 35656438, 2022). "In the current study, OVX induced cognitive impairment in mice and increased oxidative stress, serum CORT level, and expression of the inflammatory-related genes IL-1β, IL-6, and TNF-α in the frontal cortex and hippocampus." (PMID 35807554, 2022).
Cognitive impairment (continued). "Compared with the dexmedetomidine group, IL-1β, TNF-α, and MDA levels in the hippocampus of the atipamezole and yohimbine groups increased, and cognitive impairment was aggravated." (PMID 35945306, 2022). "Here, VX-765 reversed cognitive deficits without altering increased pro-inflammatory Iba1+-microglia, Il-1β, TNF-α, and GFAP+-astrocytes, thereby seemingly excluding inflammation as a driver of cognitive impairment." (PMID 36220815, 2022). "In this study, the levels of 5-HT, GABA, and BDNF in the blood of premature rats with cognitive impairment decreased, while that of GR, CRH, IL-6, and TNF-α increased, in comparison to the control group." (PMID 36061856, 2022). "Multivariate analysis showed that 95% CI of cytokines IL‐6, IL‐1β, TNF‐α, IFN‐α, and cognitive function was high, indicating a significant correlation between cognitive impairment and these cytokines." (PMID 34939360, 2022). "For instance, it has been reported that GMF contributes to cognitive deficits in mice, which may be associated with the stimulation of the MAPK and NF-κB signaling pathways, resulting in the up-regulation of pro-inflammatory cytokines such as TNF-α and IL-1β in astrocytes." (PMID 35974336, 2022). "In a study comparing the CSF levels of TNFα in patients with mild cognitive impairment (MCI) versus age-matched healthy controls, TNFα was markedly increased (p = 0.0009) in the patients with MCI." (PMID 35844236, 2022). "An increase in pro-inflammatory mediators, such as IFN-ɣ and TNF-α, contributes to the immune response, microglial activation, and polarization of the immune response towards the Th1 profile and may contribute to acute and late cognitive deficits of CM in children." (PMID 36505414, 2022). "Short-term (i.e., 10-24 weeks) moderate- to high-intensity strength training reduced LPS–IL-6, LPS, IL-1β, LPS–TNF-α and circulating concentrations of TNF-α and increased IL-10 in healthy elderly women and older people with cognitive impairment, respectively." (PMID 33936044, 2021). "Furthermore, inhibition of sEH reduces cognitive impairment in AD mouse models by reducing OS, endoplasmic reticulum (ER) stress and, most importantly, by reducing mediators of neuroinflammation, such as tumor necrosis factor (TNF-α) and interleukin 1 beta (IL-1β)." (PMID 33810307, 2021). "In the present study, the repeated injection of LPS induced activation of NF-κB and expression of IL-1β and TNF-α and suppressed expression of BDNF and phosphorylation of CREB in mouse brain, resulting in cognitive impairment, as previously reported." (PMID 34579150, 2021). "Activated microglia were found to participate in the secretion of pro-inflammatory cytokines, including IL-1β, IL-6, TNF-α, and TGF-β, thus aiding the development of cognitive impairment in individuals with neurological disorders." (PMID 35153660, 2021). "Residual schizophrenia, and its most known manifestation (cognitive impairment), is characterized by a typical biochemical decrease in BDNF and TNF-α, and at the same time an increase in IL-2, IL-6, and IL-8." (PMID 34434228, 2021). "Many studies have documented that the release of TNF-α and downstream NF-κB can breach the BBB, facilitate the migration of macrophages into the hippocampus, activate glial cells, and eventually lead to cognitive deficits after peripheral surgery." (PMID 32738920, 2020). "Interleukin-6 (IL-6) and tumor necrosis factor-α (TNF-α) have also been reported as inflammatory parameters, which are the important factors to lead to sarcopenia and the development of cognitive impairment." (PMID 32066390, 2020). "Treatment with NaHS significantly decreased the cognitive impairment of rats after SAH and simultaneously reduced the expression of TNF-α, TLR4, and NF-κB p65 and alleviated the nuclear translocation of NF-κB p65 (p < 0.05)." (PMID 32754015, 2020).
Cognitive impairment (continued). "In our present study, the degree of cognitive impairment following TZB therapy and the compensatory effects of ATV were confirmed using a passive avoidance test and measuring the levels of IL-6, IL-1β, and TNF-α." (PMID 30754707, 2019). "β-Asarone improved cognitive impairment, alleviated Aβ deposition and hippocampal damage, and inhibited GFAP, AQP4, IL-1β, and TNF-α expression." (PMID 29599803, 2017). "Perhaps, lowering TNF-α levels by TXM-CB3, as shown in Zucker rat brain, contributes to the recovery of cognitive impairment post mTBI." (PMID 27285176, 2016). "The administration of minocycline in 8-month-old 3xTg-AD mice was also shown to prevent cognitive deficits and to decrease insoluble Aβ and soluble fibrils via the reduction of inflammatory agents such as GFAP, TNF-α and IL-6." (PMID 22339795, 2012). "Neuroinflammation, cognitive deficits, impaired plasticity, and increased L-VSCC activity were all ameliorated in aged rats following chronic treatment with the novel anti-TNF biologic XPro1595." (PMID 22666474, 2012). "We, and colleagues, have previously shown that TNFα released from HIV infected or activated monocytes/microglia is a major contributor to HIV-induced neuroinflammation that leads to neuron damage and cognitive impairment." (PMID 20686703, 2010). "First, we hypothesized that TFDM, possibly through the Tumor necrosis factor-alpha (TNF-α)/Nuclear factor kappa B p65 (NF-κB p65) signaling pathway, would minimize neuroinflammation and control cognitive impairment following VaD." (PMID 40843367, 2025). "Anti‐TNF‐α, which is unable to cross the BBB, mitigates peripheral inflammation in rats by addressing chronic hyperammonemia‐induced neuroinflammation, neurotransmission changes, and cognitive deficits." (PMID 41141377, 2025). "Our key findings demonstrated that both rifaximin and lactulose significantly decreased serum and cerebrospinal fluid ammonia levels, improved cognitive deficits in MHE rats, and reduced systemic inflammation, specifically by lowering portal LPS levels and serum TNF-α and IL-1β." (PMID 40526631, 2025). "Another significant mechanism is immune dysregulation and neuroinflammation, where environmental toxins activate pro-inflammatory cytokines such as IL-6 and TNF-α, which in turn lead to chronic neuroinflammation, worsening ASD-related behavioral and cognitive deficits." (PMID 40442748, 2025). "Similarly, captopril decreased the deleterious impact of TNF on the BBB integrity in addition to repressing IL-6 levels following lipopolysaccharide intoxication in an experimental model of learning and cognitive deficits in rats." (PMID 39809925, 2025). "They further found that OBB or OBB‐NC administration can reduce long‐term neuropsychiatric complications such as anxiety, depression, and cognitive impairment, as well as inhibit the HMGB1‐mediated TLR4/NF‐κB pathway in microglia by downregulating the levels of TLR4, HMGB1, NF‐κB, TNF‐α and IL‐6." (PMID 40824273, 2025). "To identify biomarkers specific to HF and cognitive impairment, we showed that serum biomarkers for neurodegenerative disease, NfL, and cytokines, IL-6, IL-12p40, IL-15, MIP-1α, TNFα, and TNFβ, levels were significantly higher in HF participants compared to healthy control participants." (PMID 41200931, 2025). "Additionally, they influence the concentrations of pro-inflammatory cytokines such as tumor necrosis factor-α (TNF-α) and interleukin-6 (IL-6), which contribute to alleviating primary symptoms, including cognitive impairments." (PMID 40612741, 2025). "Elevated levels of IL-6, TNF-α, and C-reactive protein (CRP) have been documented in individuals with LDs, suggesting that immune dysregulation may contribute to cognitive impairments." (PMID 40150106, 2025). "Th1-biased cytokines, including IL-1β, tumor necrosis factor (TNF), and IFN-γ, may contribute to persistent cognitive impairment following bacterial meningitis." (PMID 38368403, 2024).
Cognitive impairment (continued). "In this study, we examined TNF-α levels in 34 healthy volunteers (HLT) and 99 patients, including 30 with subjective cognitive impairment (SCI) and 30 with mild cognitive impairment (MCI), which are considered preclinical stages that can evolve into AD, and 39 with AD (AD)." (PMID 38397814, 2024). "Tumor necrosis factor‐alpha (TNF‐α) levels, adjusted hippocampal volume (HVa), global 18F‐florbetapir standardized uptake value ratios (SUVR), and cognitive characteristics of the non‐mild cognitive impairment major depressive disorder (MCI MDD), MCI MDD, and the control subjects." (PMID 39236111, 2024). "A recent study showed that LDL -C activates the secretion of pro- inflammatory mediators such as tumor necrosis factor alpha and interleukin-6 and decreased the BBB membrane injury, a contributory factor to the development and progression of cognitive impairment." (PMID 37098461, 2023). "The present studies demonstrate that Mn exposure in WT mice induced motor deficits, cognitive impairment, and dopaminergic dysfunction in the nigrostriatal pathway with a concomitant increase in LRRK2 and TNF-α protein levels in the basal ganglia, which were further exacerbated in LRRK2 G2019S mice." (PMID 37269951, 2023). "According to the current results, ChA treatment may have promising potential to improve demyelination‐induced cognitive impairment, possibly through modulating BDNF and TNFα levels, which reduces demyelination." (PMID 37403256, 2023). "The levels of 5-HT, GABA, and BDNF in the blood samples from the premature rats with cognitive impairment were significantly lower than that from the normal control group, while the serum levels of GR, CRH, IL-6, and TNF-α were significantly up-regulated in rats with cognitive problem." (PMID 36061856, 2022). "The higher dose of LEVE (200 mg/kg) was found to be more effective in reducing the cognitive defects induced by DOX and the treatment also decreased acetylcholinesterase and the levels of neuroinflammatory mediators such as COX-2, PGE2, NF-κB, and TNF-α in brain homogenate." (PMID 36364190, 2022). "It is worth noting that G-CSF is not the only key molecular regulating the cognitive deficits due to Pb exposure, which was partly demonstrated by the consistent performance of IL-6 and TNF-α cytokines, as well as the ensuing crucial incidents of microgliosis." (PMID 35928850, 2022). "In addition, administration of echinomycin rescues cognitive deficits, ameliorates HIF-1α and BNIP3L-mediated neuronal pyroptosis and damaged mitochondrial structures, and decreases the expression of TNF-α and IL-6 in the hippocampus." (PMID 36569834, 2022). "Pretreatment with dexmedetomidine alleviated intestinal injury and decreased the serum and hippocampal levels of NE, IL-1β, TNF-α, and MDA at 24 h after intestinal ischemia reperfusion, decreased TH-positive neurons in the locus coeruleus, and ameliorated cognitive impairment." (PMID 35945306, 2022). "Nevertheless, the mechanism of SERUM TNF-α and iNOS involved in cognitive impairment in schizophrenia is not completely clear and only preliminary studies have been carried out." (PMID 36246695, 2022). "TNF-α antagonism has provided encouraging findings in improving depressive symptoms in chronic inflammatory diseases, but direct studies of TNF-α in cognitive impairment in MDD are lacking." (PMID 36406755, 2022). "Moreover, LDHB deficiency-induced gliosis increased the production of inflammatory mediators (TNF-α, Nf-ĸB, and NOS2), and revealed cognitive deficits." (PMID 35204143, 2022). "In fact, in one experiment, drebrin levels in the superior temporal cortex were found to be approximately 35% lower in subjects with mild cognitive impairment, who exhibited upregulation of TNF-α and IL-6, than in subjects without cognitive impairment." (PMID 36550479, 2022).